EGFR (epidermal growth factor receptor)
Diseases named in the same sentence as EGFR in open-access papers (continued):
Sharing a sentence is not in itself a finding about the gene and the disease.
tumor (continued). "It has been reported that EGFR-TKI can enhance the anti-tumor effect of anti-PD-1 treatment in preclinical studies." (PMID 39004699, 2024). "It was found that both CD44 and E-cadherin decreased with the grade of tumor, while EGFR and vimentin increased with tumor de-differentiation." (PMID 39050298, 2024). "It was found that this combination therapy has a strong synergistic anti-tumour effect on tumour cells with high EGFR expression of HT-29, in addition to a significant enhancement of anti-angiogenic effect." (PMID 39046631, 2024). "This marks the inaugural report of Tandyukisin as an EGFR inhibitor, although its anti-tumor properties were previously identified in a study by Takeshi Yamada’s group in 2015, which isolated a new decalin derivative from the marine sponge Halichondria okadai." (PMID 38751788, 2024). "Nevertheless, EGFR targeting through immune-mediated mechanisms is effective in killing tumor cells by ADCC, both in vitro and in vivo." (PMID 38510242, 2024). "The human patient case study revealed a population of MET-amplified tumor cells that were resistant to EGFR-/BRAF-targeted therapy." (PMID 39626159, 2024). "Our in vivo results indicate that the inhibition of HIFs by FM19G11, as well as its downstream effectors of the pathway, VEGF/VEGFR1 autocrine loop, and EGF/EGFR autocrine loop markedly reduced tumor growth as well as the expansion of the EpCAM+/ABCG2+ cells." (PMID 39963656, 2024). "EGFR806-CAR T cells effectively and selectively target EGFR-expressing tumor cells in vitro and in vivo." (PMID 39364321, 2024). "So, the question remains: which culture condition more closely recapitulates the tumor in terms of EGFR activity?" (PMID 38538642, 2024). "Targeted ligand modification decorates nanodrug surfaces with specific ligands that bind to receptors overexpressed on tumor cells, such as transferrin receptor (TfR), folate receptor (FR), and epidermal growth factor receptor (EGFR)." (PMID 39834835, 2024). "EGFR-CAR-NK cells demonstrated a substantial inhibition of tumor growth in mouse models derived from triple-negative breast cancer (TNBC) cell lines (CLDX) and patient-derived xenografts (PDX)." (PMID 39633491, 2024). "This choice is based on mAb806’s ability to bind both to EGFRvIII and to full-length EGFR expressed due to gene amplification while also exhibiting tumor specificity." (PMID 39506843, 2024). "These scFv-bEVs bound to EGFR-overexpressed cancer cells more than control bEVs and also displayed enhanced tumor targeting in EGFR-expressing models in vivo." (PMID 38690563, 2024). "Membrane proteins such as epidermal growth factor receptor and tumor necrosis factor receptors play critical roles in tumor signaling pathways." (PMID 38218878, 2024). "Recent studies have demonstrated the utility of ctDNA analysis for diagnosing and monitoring tumor evolution in patients with mCRC who are treated with EGFR inhibitors." (PMID 39064004, 2024). "Pan-HER TKI can hinder tumor progression by targeting other receptors (e.g., EGFR) and can overcome primary resistance to some anti–HER-2 drugs." (PMID 39045556, 2024). "Similar oligomer fractions would be expected for Ba/F3 + T766M tumor xenograft cells, which we found to express ~2 × 105 EGFR copies/cell." (PMID 38503739, 2024). "Dysfunctional EGFR activation can drive tumor development, spread, resistance to apoptosis, and angiogenesis, fueling the tumor’s growth and metastasis." (PMID 38474160, 2024). "Tumor growth inhibition has been recently demonstrated in vivo in a murine model of squamous cancer using a liposome-MB complex loaded with EGFR siRNA combined with US." (PMID 39088581, 2024). "Combination therapy of anti-CD47 antibodies with EGFR inhibitors demonstrates more effective inhibition of tumor growth." (PMID 39223632, 2024).
tumor (continued). "So, patients with liver metastases with tumor budding and/or KRAS mutational status respond poorly to anti-EGFR therapy." (PMID 38248029, 2024). "The researchers proposed the ET axis as a mechanism of drug resistance in EGFR-mutated NSCLC through vasoconstriction, reducing drug delivery to the tumor." (PMID 38785410, 2024). "We subsequently analyzed the single-cell transcriptomic landscape of the tumor and revealed that tumor cells exhibited relatively high EGFR and MET expression in response to pembrolizumab treatment alone." (PMID 38916448, 2024). "Our findings demonstrated that simultaneous inhibition of EGFR and α5β1 integrin activation and signaling led to an overall decrease in VM and tumor cell motility in vitro and tumor growth and metastasis in vivo." (PMID 38315147, 2024). "According to our design, upon activation by the AND logic gate, HA-BPY-GEF-NPs releases GEF, which inhibits EGFR expression and blocks related signaling pathways, thereby suppressing the growth and metastasis of tumor cells." (PMID 39321294, 2024). "The analysis revealed most cells in tumor microenvironment including stromal cell expressed EGFR, NFE2, and FSL1 genes while a lower number of cells expressed CDH3, ARL4D, and SH3RF2." (PMID 38172584, 2024). "These agents exploit the overexpression or mutations of specific receptors, such as the Epidermal Growth Factor receptor (EGFR) and αVβ3 integrin, which are pivotal in tumor growth, angiogenesis, and metastasis." (PMID 39126121, 2024). "Based on our data, levels of expression of the mutant form and activation of EGFR and its dimerizing partners varied significantly across MCPs established from the same tumor and affected response to treatment with different RTK inhibitors." (PMID 39061010, 2024). "High EGFR levels in HNSCC indicate poor prognosis, as EGFR promotes tumor growth, invasion, and metastasis." (PMID 39459468, 2024). "Our in vitro data demonstrate that EGFR/EGFRvIII tumor cells are more sensitive to saracatinib than EGFR WT tumor cells." (PMID 38892466, 2024). "For example, glabridin can be combined with small peptides targeting EGFR or human epidermal growth factor receptor 2 (HER2) to achieve selective delivery to tumor sites." (PMID 39723390, 2024). "All NKCEs generated in the study demonstrated the ability to eliminate EGFR-expressing cancer cells; however, the potency and efficacy of tumor cell killing varied significantly depending on the specific epitopes on NKp30 that each NKCE targeted." (PMID 39911822, 2024). "In this project, we evaluated the effect of the GHRH-R antagonist MIA-690 in combination with the EGFR inhibitor Gefitinib on different tumour processes in PC-3 cells." (PMID 39456984, 2024). "In summary, the emerging roles of COX-2 and EGFR as promising biomarkers in predicting tumor progression suggest potential avenues for future therapies." (PMID 38248333, 2024). "The prognostic indicators incorporated for LUSC include Age, EGFR mutation, EML4-ALK translocation, Gender, TNM stage, new tumor event, and Tumor stage." (PMID 39331207, 2024). "Dual inhibition of HER2 and EGFR provides an approach to reduce tumor cell growth signaling cascades." (PMID 38355949, 2024). "GAS6/AXL is active also between START and tumor-enriched C25fibro (the major CAF subtype in EGFR-mutant ADCs) until treatment with Unesbulin stops it completely." (PMID 38546390, 2024). "Experimentally, we found that suppression of DUSP5 significantly inhibited the TGF-β signaling pathway-mediated EMT, thus impeding tumor metastasis and EGFR-TKI resistance." (PMID 38872157, 2024). "As a proof of concept, we also wanted to demonstrate the potential of this VLP–Z domain construct as a platform to develop a nanocarrier to target tumor cells overexpressing EGFR." (PMID 38673914, 2024). "Single-cell RNA transcriptomic analysis showed that pembrolizumab alone induced tumor invasive mechanism by upregulation of EGFR and MET signaling." (PMID 38916448, 2024).
tumor (continued). "EGFR and its downstream signalling pathways have been the most extensively studied key player in the tumor development of NSCLC." (PMID 39066920, 2024). "One study highlighted the need for EGFR T790M genotyping of tumor samples obtained after disease progression in patients treated with Osimertinib to guide treatment decisions." (PMID 38584122, 2024). "The aberrant expression of EGFR is closely related to the invasion and metastasis of tumor cells, tumor angiogenesis, chemotherapy resistance, and abnormal cell proliferation." (PMID 38983928, 2024). "Cetuximab, similar to panitumumab, is an EGFR inhibitor that suppresses tumor cell growth and metastasis by inhibiting the EGFR signaling pathway." (PMID 38375031, 2024). "Apoptosis can be induced in tumor cells with high EGFR expression through ADCC and complement-dependent cytotoxicity mediated by EGFR-targeting antibodies, such as cetuximab." (PMID 39650651, 2024). "In certain instances, inhibiting EGFR can cause an increase in the expression of VEGFR-2, which in turn speeds up the signaling for tumor growth independently of EGFR." (PMID 39569013, 2024). "Conceivably, the ability of tumor cells to rapidly adapt to the drug-tolerant state upon initiation of TKI administration is crucial for the survival of tumor cells during the early stage of EGFR-targeted therapy." (PMID 39041204, 2024). "Passive cavitation detection in vivo demonstrated that inertial cavitation was present in the tumor during EGFR siRNA LPX + UTMC treatment." (PMID 38577322, 2024). "Unfortunately, acquired resistance will inevitably occur in patients after receiving EGFR-TKIs, leading to tumor recurrence and metastasis." (PMID 39533233, 2024). "In 2016, anti-EGFR nanobodies were genetically fused with a GPI-anchor signal peptide, enhancing the targeting capabilities of exosomes towards EGFR-expressing tumor cells." (PMID 39204374, 2024). "Combining EGFR inhibitors and ICIs warrants further investigation in patients with EGFR-amplified tumours." (PMID 38744099, 2024). "Sortilin is an important regulator with potential tumour-suppressor function by limiting EGFR signalling." (PMID 38893272, 2024). "In tumor cells, EGFR frequently undergoes oncogenic alterations, resulting in aberrant signaling that, in turn, promotes cancer cell survival, invasion, and metastasis." (PMID 38689087, 2024). "Aberrant activation of the epidermal growth factor receptor (EGFR), characterized by dysregulated cascade reactions, plays a pivotal role in the uncontrolled formation of tumor masses and the release of cytokines." (PMID 38844562, 2024). "Cetuximab, an FDA-approved monoclonal antibody for HNSCC, inhibits EGFR signal transduction, which promotes antigen presentation and immune response to the tumor cells." (PMID 38398094, 2024). "GLUT1 interacts directly with p-EGFR protein and activates EGFR signaling pathways to promote tumor progression." (PMID 38831321, 2024). "In our study we have shown that avelumab (anti–PD-L1) and cetuximab (anti-EGFR) enhance macrophage-mediated phagocytosis of target tumor cells in the presence of CV1 monomer." (PMID 38828721, 2024). "In tumor cells with high expression of EGFR, the expression levels of CD47 are also upregulated, leading to enhanced growth and immune evasion capabilities." (PMID 39223632, 2024). "The overexpression of HER2 plays an important role in inducing resistance to the EGFR target therapy and promotes multiple tumor progression." (PMID 39107736, 2024). "Given the role of nuclear EGFR in drug resistance and tumor malignancy, researchers have investigated strategies to reduce its nuclear translocation by inhibiting Akt and Src-induced EGFR phosphorylation." (PMID 39404930, 2024). "EGFR expression was concordant between CHCs and tumor tissue in three of four patients, all of whom saw decreases in response to treatment." (PMID 39518088, 2024).
tumor (continued). "The activation of EGFR signaling in tumor cells initiates a cascade that leads to the recruitment of TAMs, which subsequently promote the upregulation of EMT-TFs in NSCLC." (PMID 39286635, 2024). "Epidermal growth factor receptor (EGFR)-targeted drugs (erlotinib, etc.)are used to treat multiple types of tumours." (PMID 38604999, 2024). "Tumor uptake was favorable and correlated well with intratumoral distribution determined by autoradiography and EGFR immunohistochemistry." (PMID 39239273, 2024). "EREG is poorly expressed in most normal tissues, but overexpressed EREG triggers its downstream signaling pathway and promotes tumor progression while binding to EGFR." (PMID 38318160, 2024). "One potential target is the epidermal growth factor receptor (EGFR), which is frequently mutated and activated in NSCLC, promoting tumour growth and survival." (PMID 38982031, 2024). "Western blot examination of tumor protein extracts from the corresponding serially collected samples confirmed suppression of EGFR Y1068 phosphorylation starting from 6 hours after osimertinib dosing and was undetectable by 72 hours." (PMID 39041204, 2024). "EGFR, a 170-kDa transmembrane tyrosine kinase receptor, is detected in various malignant cells and has been reported to play a vital role in tumor development and progression." (PMID 38686044, 2024). "Certain lncRNAs enhance the expression of oncogenes, thereby facilitating tumor cell proliferation, survival, and resistance to EGFR-TKI." (PMID 39872524, 2024). "These mutations regulate the growth, proliferation, and survival of tumor cells through abnormal activation of the EGFR signaling pathway, which includes critical downstream pathways such as PI3K/AKT and JAK/STAT." (PMID 39640262, 2024). "High expression of FAM66C activates EGFR-ERK signaling by inhibition of the proteasome pathway promoting tumor growth." (PMID 39143529, 2024). "EGFR stimulates tumour growth by modulating dimerisation of Ras proteins, which leads to a phosphorylation cascade that activates the PI3K/AKT signaling pathway." (PMID 38212810, 2024). "All patients underwent maximal safe resection of the recurrent tumor to confirm the EGFR amplification as target, and an intraventricular subcutaneous reservoir (Ommaya) was placed in the same procedure." (PMID 38592708, 2024). "The ABE assay results confirmed that the palmitoylation level of EGFR increased in tumor cells with PA/OA treatment in vitro and primary tumor cells isolated from NAFLD liver." (PMID 38263401, 2024). "After the detection of EGFR amplification, switching to cetuximab resulted in significant tumor shrinkage, demonstrating the impact of real-time ctDNA findings in guiding effective treatment adjustment." (PMID 39796090, 2024). "There were 38 patients (42.70%) harboring mutant EGFR gene in their tumor tissues, including 16 cases of exon 19 deletion, 18 cases of exon 21 L858R missense mutation, and 4 cases of exon 20 T790M mutation." (PMID 39634906, 2024). "In this manuscript, we explore the relationship between ERO1A expression and the critical determinants of progression of EGFRMUT-LUAD, including colony and tumor sphere formation, spheroid growth, matrix secretion and sensitivity to EGFR inhibitors." (PMID 39496753, 2024). "This exploratory analysis included randomization (1:1) of patients with EGFR and ALK mutations, stratified by PD-L1 tumor cell (TC) expression (≥25% vs. <25%)." (PMID 38927911, 2024). "Studies have shown that tumor resistance to radiotherapy is closely related to the activation of epidermal growth factor receptor (EGFR), and the amplification of EGFR in GBM results in reduced sensitivity of GBM to radiotherapy." (PMID 39564524, 2024). "By blocking the binding of EGF ligands and TGF-α to EGFR, panitumumab inhibits tumor growth and triggers tumor regression." (PMID 39769315, 2024).
tumor (continued). "In tumors with HPV16/18E6 oncoprotein expression or mutant EGFR, PD-L1 expression is induced, promoting tumor growth and invasiveness in NSCLC." (PMID 39409943, 2024). "The binding characteristics of each TKI vary according to a specific EGFR mutation, and the choice of TKI agents is based on the unique molecular features of the tumor." (PMID 38793045, 2024). "It was found that the tumor microenvironment (TME) of EGFR-mutated NSCLC showed a "cold" phenotype, including low expression of PD-L1 on tumor cells, low infiltration of CD8+ T cells, and high infiltration of immunosuppressive regulatory cells in the TME." (PMID 39004699, 2024). "In contrast, larger vessels from EGFR-expressing tumours were enriched for Birc2 (survivin), Socs2 (suppressor of cytokine signalling 2) and Srsf2 (serine and arginine-rich splicing factor 2)." (PMID 38570528, 2024). "XHP downregulated tumor stem cell markers through modulation of the CD133/EGFR/Akt/mTOR pathway and inhibited tumor stem cell enrichment and self-renewal, preventing the malignant progression of glioma." (PMID 38957318, 2024). "For patients with EGFR wild type tumours, treatment duration was generally shorter, with median TTD1 (95% CI), TTD2, and TTD3 of 4.0 months (3.3, 4.6), 2.8 months (1.9, 4.8), and 2.1 months (1.3, 5.8), respectively." (PMID 38668049, 2024). "Recent clinical trials have reported that metastatic CRC with tumor-promoting mutations in KRAS, PI3KCA, and BRAF is resistant to anti-EGFR therapy." (PMID 38542151, 2024). "We developed an orthotopic xenograft tumor model in C57BL/6 mice (n = 5) to understand the role of EGFR in tumorigenesis." (PMID 38522013, 2024). "EGFR/MEK inhibitors combined with the covalent TEAD inhibitor MYF-01-37 promoted the apoptosis of dormant tumor cells." (PMID 38499647, 2024). "One example in this context is the Epidermal Growth Factor Receptor (EGFR, also denoted as HER1), which is highly expressed in numerous tumor entities and, therefore, represents an important target structure for specifically accumulating radioligands." (PMID 39458921, 2024). "Conversely, HER2, another critical biomarker, belongs to the epidermal growth factor receptor (EGFR) family and plays a role in numerous tumor signaling pathways." (PMID 38256428, 2024). "ARAF amplification potentially fosters conditions that promote tumor cell survival and neuroendocrine marker transcription under EGFR-TKIs, particularly in female patients with EGFR exon 19 deletion." (PMID 39456595, 2024). "The fluorescence imaging and in vivo xenograft tumor imaging suggest that probe C34 particularly responded to tumor cells overexpressing EGFR." (PMID 39518106, 2024). "Next, we investigated the cellular binding specificity of the affibody molecules to NPC-positive tumor cells over-expressing Axl and EGFR using an indirect immunofluorescence assay." (PMID 39594573, 2024). "By engaging both targets, EGFRxHER2 heterodimeric T-BsAb exhibited potent anti-tumor effects if CDX or PDX were EGFR+HER2+ double-positive with the potential to spare single-positive normal tissue." (PMID 38650005, 2024). "These mutations, which account for about 85% of observed EGFR mutations in NSCLC, lead to constitutively active EGFR signaling that promotes tumor growth." (PMID 38474205, 2024). "Tumor cells overexpress oncolytic virus receptors like sialic acid and EGFR, critical for viral transmission, replication, and initiation of endocytic signaling pathways." (PMID 39141643, 2024). "Recently, there has been a growing interest in combining EGFR-TKIs with RT to enhance the anti-tumor activity and overcome resistance." (PMID 39772073, 2024). "EGFR is overexpressed in a significant majority of HNSCC cases and is associated with aggressive tumor behavior and resistance to conventional therapies." (PMID 39339232, 2024).